EXOC1 (exocyst complex component 1)
Description:
Component of the exocyst complex involved in the docking of exocytic vesicles with fusion sites on the plasma membrane. (Microbial infection) Has an antiviral effect against flaviviruses by affecting viral RNA transcription and translation through the sequestration of elongation factor 1-alpha (EEF1A1). This results in decreased viral RNA synthesis and decreased viral protein translation.
Synonyms: SEC3; SEC3L1; FLJ10893; BM-102; Sec3p
Tractability: Antibody: UniProt places it where antibodies can reach, with high confidence; its Gene Ontology location is reachable by antibodies, with high confidence. PROTAC: ubiquitination databases record sites on it; its protein half-life has been measured.
Gene: Protein-coding gene on chromosome 4 (55,853,628 to 55,905,096, forward strand). Ensembl gene ENSG00000090989.
Subcellular location: Midbody, Midbody ring; Cytoplasm; Cytoplasm, perinuclear region; Cell membrane
Subcellular location (Human Protein Atlas): Microtubules; Plasma membrane; Cytosol
Pathways (Reactome):
Disease: Dengue virus activates/modulates innate and adaptive immune responses
Metabolism of proteins: Insulin processing
Organelle biogenesis and maintenance: VxPx cargo-targeting to cilium
Vesicle-mediated transport: Translocation of SLC2A4 (GLUT4) to the plasma membrane
Gene Ontology:
Molecular function: protein binding; phosphatidylinositol-4,5-bisphosphate binding
Biological process: exocytosis; Golgi to plasma membrane transport; membrane fission; mitotic cytokinesis; regulation of macroautophagy
Cellular component: cytoplasm; cytosol; membrane; plasma membrane; exocyst; Flemming body; perinuclear region of cytoplasm
Genetic constraint (gnomAD): Loss-of-function variants: 49 observed, 90.63 expected, observed/expected ratio (o/e) 0.54, 90% interval 0.43 to 0.69. The upper end of that interval is the gene's LOEUF score, 0.69, which puts it in group 2 of 6, group 1 being the genes least tolerant of losing a copy. Missense variants: 755 observed, 984.25 expected, observed/expected ratio (o/e) 0.77, 90% interval 0.72 to 0.81. Synonymous variants: 324 observed, 336.16 expected, observed/expected ratio (o/e) 0.96, 90% interval 0.88 to 1.06.
Homologues: Orthologues: chimpanzee EXOC1 (100% identical), macaque EXOC1 (99% identical), dog EXOC1 (99% identical), rabbit EXOC1 (98% identical), pig EXOC1 (98% identical), mouse Exoc1 (97% identical), guinea pig EXOC1 (97% identical), rat Exoc1 (96% identical), tropical clawed frog exoc1 (87% identical), zebrafish exoc1 (85% identical), Drosophila melanogaster Sec3 (41% identical), Caenorhabditis elegans sec-3 (33% identical). Paralogues in human: STXBP6 (8% identical), EXOC1L (6% identical).
Diseases named in the same sentence as EXOC1 in open-access papers:
EXOC1 is named in the same sentence as 19 diseases in open-access papers, as found by Europe PMC text mining. Sharing a sentence is not in itself a finding about the gene and the disease. The quoted sentences say what the papers report.
cervical cancer (5 papers, 2017 to 2022). A primary or metastatic malignant neoplasm involving the cervix. "We also observed associations of borderline significance with the TIPARP rs2665390 polymorphism, which was previously found to be associated with ovarian and breast cancer, and with the EXOC1 rs13117307 polymorphism, which has been linked to cervical cancer in a large study in a Chinese population." (PMID 28505207, 2017).
breast carcinoma (4 papers, 2017 to 2025). "Further flow cytometry experiments confirmed that knockout of DIS3, TBP, or EXOC1 individually markedly increased MHC-I levels on the cell surface of breast cancer MCF7 cells." (PMID 39408874, 2024). "Six CDM genes (SRF, RAD51, PMF1, EXOSC3, EXOC1, and TSEN54) were found to be associated with the prognosis of breast cancer samples." (PMID 35096059, 2022). "The univariate and multivariate Cox regression analysis revealed that six CDM genes (SRF, RAD51, PMF1, EXOSC3, EXOC1 and TSEN54) were associated with the survival of patients with breast cancer." (PMID 35096059, 2022). "Interestingly, HNRNPL loss induces the exclusion of exon 12 in NUMB and the inclusion of exon 11 in EXOC1, suggesting a cooperative role of these two proteins in splicing regulation during breast cancer metastasis." (PMID 40323145, 2025). "Conclusively, we identified multiple genes, including DIS3, TBP, and EXOC1, as potential dual-effectors that regulate both MHC-I expression and cell survival in breast cancer." (PMID 39408874, 2024). "Furthermore, we verified partially according to KEGG functional enrichment or gene-dependency analysis and figured out multiple genes, including PIP5K1A, NCKAP1, CYFIP1, DIS3, TBP, and EXOC1, as effective gene targets for increasing MHC-I expression in breast cancer." (PMID 39408874, 2024).
cyst (2 papers, 2014 to 2025). A sac-like closed membranous structure that may be empty or contain fluid or amorphous material. "We found that depletion of oocyte-specific EXOC1, a component of the exocyst complex, impaired oocyte re-awakening and cyst breakdown, and inhibited granulosa cell proliferation during follicle growth." (PMID 39833146, 2025). "To investigate the effect of Exoc1 deletion during foetal ovarian affect cyst breakdown, we induced Cre recombination in Exoc1flox/flox::Ddx4+/CreERT2 mice at E15 and named these mice Exoc1-D-cKO-E." (PMID 39833146, 2025). "We discovered that EXOC1 was necessary for crosstalk factor intra-oocyte trafficking, which was in turn required for oocyte re-awakening, follicle growth, and cyst breakdown." (PMID 39833146, 2025). "Exoc1 is essential for regulating cytoplasmic division in mice spermatocytes, and c-KIT facilitates cyst breakdown." (PMID 39833146, 2025). "The number of follicles dropped significantly, which was not shown in the Kit cKO, suggesting that Exoc1 could also have functions that contributed to oocyte viability during cyst breakdown that were absent in Kit cKO." (PMID 39833146, 2025).
glioma (1 paper, 2023). A benign or malignant brain and spinal cord tumor that arises from glial cells (astrocytes, oligodendrocytes, ependymal cells). "However, the expression and prognosis of KIT, CHIC2, EXOC1, IGFBP7, RASL11B or USP46 in glioma are unclear." (PMID 36043552, 2023).
hydronephrosis (1 paper, 2022). Collection of urine in the renal pelvis that results in dilatation of the renal pelvis and calyces. "Exoc4/Sec8-/- mice initiate gastrulation but die shortly afterward, Exoc1/Sec3-null mice undergo peri-implantation lethality, and the conditional ablation of Exoc5/Sec10 leads to bilateral hydronephrosis and complete anuria in newborn mice leading to death shortly after." (PMID 36150098, 2022).
melanoma (1 paper, 2023). A malignant, usually aggressive tumor composed of atypical, neoplastic melanocytes. "Aberrant expression of TTC28 and EXOC1 is associated with melanoma and platelet secretion defects, respectively." (PMID 37026480, 2023).
neuroblastoma (1 paper, 2015). Neuroblastoma (NB) is the most common solid, extracranial childhood tumor. "Similar results were observed in response to bradykinin, another stimulant that induces IP3-mediated ER calcium release in EXOC1- or DISC1-knockdown differentiated neuroblastoma CAD cells." (PMID 25732993, 2015).
viral infection (1 paper, 2021). "In Chinese populations, GWAS-detected loci in EXOC1 and GSDMB genes are suspected to influence immune response to viral infection." (PMID 33794208, 2021).
cancer (4 papers, 2017 to 2024). A tumor composed of atypical neoplastic, often pleomorphic cells that invade other tissues. "To strengthen this hypothesis, we first performed siRNA-mediated knockdown of Sec3 (EXOC1) in the cancer cells, which showed a significant reduction in nanotubular cancer cell–endothelial cell and cancer cell–cancer cell connections." (PMID 34200503, 2021).
tumor (4 papers, 2014 to 2022). "NUMB, VCL, MAP3K7 and EXOC1 exon skipping events are examples of known splicing events that can be also observed in tumor tissue." (PMID 36304260, 2022). "SRF and EXOSC3 expression levels were lower in tumor tissues than in control tissues, while RAD51 and EXOC1 were significantly higher in tumor tissues." (PMID 35096059, 2022).
EXOC1 also shares sentences with these, for which no sentence is quoted: infection (3 papers); adenocarcinoma (1); COVID-19 (1); endophthalmitis (1); female infertility (1); Infertility (1); psoriasis (1); squamous cell carcinoma (1); vaginal infections (1).